SPINK5 (serine peptidase inhibitor Kazal type 5)
Diseases named in the same sentence as SPINK5 in open-access papers (continued):
Sharing a sentence is not in itself a finding about the gene and the disease.
esophageal squamous cell carcinoma (3 papers, 2019 to 2023). Esophageal squamous cell carcinoma (ESCC) is a type of esophageal carcinoma (EC) that can affect any part of the esophagus, but is usually located in the upper or middle third. "Besides, SPINK5 was downregulated in esophageal squamous cell carcinoma (ESCC) and non-small cell lung carcinoma (NSCLC) compared with in normal squamous epithelium, and SPINK5 may be a protective gene in ESCC and NSCLC28,29." (PMID 37185487, 2023).
food allergies (3 papers, 2023 to 2025). "Similarly, polymorphisms in the SPINK5 gene, which lead to abnormal skin keratinization and elevated levels of cytokines such as TSLP, are reported to be associated with food allergies." (PMID 40290033, 2025). "Also, genetic mutations affecting skin barrier proteins, such as FLG and serine protease inhibitor Kazal type 5 (SPINK5), can significantly impair the skin’s protective function, leading to food allergies." (PMID 40290033, 2025).
head and neck squamous cell carcinoma (3 papers, 2021 to 2025). A squamous cell carcinoma that arises from any of the following anatomic sites: lip and oral cavity, nasal cavity, paranasal sinuses, pharynx, larynx, and salivary glands. "Furthermore, SPINK5 expression levels have been found to be downregulated in head and neck squamous cell carcinomas (HNSCCs)." (PMID 34503205, 2021).
psoriasis (3 papers, 2009 to 2025). An autoimmune condition characterized by red, well-delineated plaques with silvery scales that are usually on the extensor surfaces and scalp. "Genes from exC3 which have established roles in AD and psoriasis include SPINK5, FLG and CDSN." (PMID 19888454, 2009). "SPINK5 is related to a skin disorder and is consistent with the clinical picture of Pt#5, who is affected with psoriasis; the possible connection with neutropenia might be explained by the expected reduced expression of LEF1, which in turn deregulates lymphocyte activity." (PMID 40725177, 2025). "KRT6A was expressed in lesional interfollicular skin in Spink5 cKO mice, consistent with the known upregulation of KRT6A expression in interfollicular keratinocytes upon trauma, wounding or hyperproliferative skin diseases such as psoriasis." (PMID 38316920, 2024).
cervical cancer (2 papers, 2020 to 2025). A primary or metastatic malignant neoplasm involving the cervix. "The aberrant expression of many mRNAs, including FGFR3, CTGF, TP63, IL36G, ADH7, SPINK5, and so on, have also been identified in cervical cancer." (PMID 32123519, 2020).
chronic rhinosinusitis (2 papers, 2017 to 2020). Chronic form of sinusitis. "Richer and collaborators (2009) showed a decreased expression of S100A7, S100A8, S100A9, and SPINK5 genes in the airway mucosal epithelium of people with chronic rhinosinusitis, which they associated with a defective epithelial barrier in this condition." (PMID 32735560, 2020). "Additionally, studies measuring SPINK5 in nasal epithelial tissue revealed that low SPINK5 expression was associated with chronic rhinosinusitis with and without nasal polyps and among those with chronic rhinosinusitis and aspirin intolerance." (PMID 28552993, 2017).
erythroderma (2 papers, 2021 to 2023). "Variants in the SPINK5 gene result in defective expression of lymphoepithelial Kazal type inhibitor (LEKTI), resulting in activation of kallikrein (KLK5) and subsequent degradation and chronic inflammation of the epidermal barrier resulting in ichthyosiform desquamating erythroderma." (PMID 36839544, 2023).
erythrokeratoderma (2 papers, 2018 to 2022). An umbrella term for a group of rare genetic skin disorders characterized by well-demarcated plaques of reddened, dry and thickened skin. "As clearly observed, no pathogenic variations in SPINK5 gene, neither in genes involved in erythrokeratoderma variabilis (EKV) were found in ILC patients (data not shown), confirming then different etiologies." (PMID 34983512, 2022).
Immunodeficiency (2 papers, 2022 to 2024). Failure of the immune system to protect the body adequately from infection, due to the absence or insufficiency of some component process or substance. "We therefore asked whether Spink5 loss-of-function in the thymic medulla can affect thymocyte development and thus contribute to immunodeficiency or autoimmune disease." (PMID 38316920, 2024). "As expected, our study identified several well-known PADs such as STAT3, WAS, DOCK8, SPINK5, and CARD11 that are classified according to the IUIS as combined immunodeficiency with or without syndromic features." (PMID 35273610, 2022).
liver cancer (2 papers, 2021 to 2022). An epithelial or non-epithelial malignant neoplasm that arises from the liver. "Six genes (BIRC5, CACYBP, NR0B1, RAET1E, SPINK5, SPP1) were up-regulated in the liver cancer tissues compared to the normal tissues in the TCGA HCC dataset, and S100A8 was downregulated." (PMID 33568167, 2021).
melanoma (2 papers, 2022). A malignant, usually aggressive tumor composed of atypical, neoplastic melanocytes. "SPINK5 is a tumor suppressor protein that regulates EMT on melanoma cells, and when overexpressed inhibits metastasis abilities." (PMID 36273071, 2022). "Migration and wound healing assays showed that the miR-5100/SPINK5/STAT3 axis promotes melanoma cell metastasis; the mechanism was proven by initiation of epithelial-mesenchymal transition." (PMID 35705923, 2022).
renal carcinoma (2 papers, 2021 to 2022). A carcinoma arising from the epithelium of the renal parenchyma or the renal pelvis. "In addition, SPINK5 is demonstrated to be one of the downstream target genes of G9a, and G9a promotes the development of renal cancer through epigenetic silencing of tumor suppressor gene SPINK5." (PMID 35559246, 2022).
renal cell carcinoma (2 papers, 2022 to 2025). "Furthermore, SPINK5 serves as a downstream target of G9a, a histone lysine methyltransferase observed in renal cell carcinoma (RCC)." (PMID 40872585, 2025). "G9a downregulates the expression of SPINK5 through the methylation of H3K9me2, thereby promoting the proliferation, migration and invasion of renal cell carcinoma (RCC) cells." (PMID 35223512, 2022).
skin infection (2 papers, 2019 to 2024). An inflammatory process affecting the skin, caused by bacteria, viruses, parasites, or fungi. "Collectively, these data suggest that in Spink5 cKO mice the main gene expression changes take place in the skin, while the gene expression changes observed in lymph nodes might reflect secondary events resulting from the systemic immune response to skin infection." (PMID 38316920, 2024).
actinopathy (1 paper, 2022). "Mechanisms underlying the allergic immune dysregulation seen in these conditions range from impaired epithelial barrier (SPINK5), to actinopathy (WAS, DOCK8), to altered antigen receptor (CARD11) and cytokine signaling (STAT3)." (PMID 35273610, 2022).
AIDS (1 paper, 2022). A syndrome resulting from the acquired deficiency of cellular immunity caused by the human immunodeficiency virus (HIV). "Large condyloma acuminata are frequently reported in patients with primary (e.g., DOCK8 or SPINK5 deficiencies) and secondary (e.g., AIDS, solid organ transplantation) immune defects." (PMID 35562936, 2022).
atherosclerosis (1 paper, 2024). A disease characterized by the build-up of fatty material and calcium deposition in the arterial wall resulting in partial or complete occlusion of the arterial lumen. "Moreover, we identified several novel genes not previously linked to SMCs in atherosclerosis, such as Anxa4, Cd276, inter-alpha-trypsin inhibitor-4 (Itih4), Myof, Pcdh11x, Rab31, Serpinb6b, Slc35e4, Slc8a3, and Spink5." (PMID 38289873, 2024). "The gene list included well-known atherosclerosis-associated genes Serpina3,42Cemip,43Thbs1,44Lum,45 and Spp146,47 but also novel genes without previous association to SMC function in atherosclerosis, such as Anxa4, Cd276, Itih4, Myof, Pcdh11x, Rab31, Serpinb6b, Slc35e4, Slc8a3, and Spink5." (PMID 38289873, 2024).
Atrophy (1 paper, 2024). Any weakening or degeneration, especially through lack of use. "Similar to thymic atrophy, the increase of serine protease activity in Spink5 cKO thymi was not affected by systemic treatment with broad-spectrum antibiotics and the protease activity levels correlated significantly with thymic atrophy." (PMID 38316920, 2024).
Autoimmunity (1 paper, 2025). The occurrence of an immune reaction against the organism's own cells or tissues. "The enrichment and burden tests performed in comparison with a control group underline that the products of expression by the variants involved belong to the autoimmunity and immune regulation pathways (i.e., SPINK5, PTPN22 and PSMB9)." (PMID 40725177, 2025).
autosomal dominant Job ́s syndrome (1 paper, 2020). "These human hyper-IgE syndromes (HIES) include the autosomal dominant Job ́s syndrome and autosomal recessive PGM3 (phosphoglucomutase 3) and SPINK5 (Serine Peptidase Inhibitor Kazal Type 5) syndromes, that can be successfully treated with anti-IgE antibody therapy or stem cell transplantation." (PMID 32695309, 2020).
childhood asthma (1 paper, 2021). "Although a significant attenuation of Spink5 was thought to be involved in childhood asthma through the interaction with TSLP in Has2+/−-OVA mice, the expression levels of Tslp were not significantly different between WT-OVA and Has2+/−-OVA mice." (PMID 35069543, 2021).
chorioamnionitis (1 paper, 2024). A morphologic finding indicating inflammation of the fetal sac membranes. "Membranes with chorioamnionitis display increased miR-223 and miR-338 expression, and miR-223 target genes (SPINK5, TGFB2, and IFNB1) are involved in the biological processes of negative regulation of immune and anti-inflammatory responses." (PMID 39574982, 2024).
chronic obstructive pulmonary disease (1 paper, 2025). A chronic and progressive lung disorder characterized by the loss of elasticity of the bronchial tree and the air sacs, destruction of the air sacs wall, thickening of the bronchial wall, and mucous accumulation in the bronchial tree. "GWASs have further associated SPINK5 variants with lung phenotypes (for example, chronic obstructive pulmonary disease, forced expiratory volume) and pancreatitis." (PMID 41310232, 2025).
diabetes mellitus (1 paper, 2023). A metabolic disorder characterized by abnormally high blood sugar levels due to diminished production of insulin or insulin resistance/desensitization. "IL1R2 and SPINK5 plays an important role in the diabetes mellitus and obesity." (PMID 36837510, 2023).
head and neck cancer (1 paper, 2026). A primary or metastatic malignant neoplasm affecting the head and neck. "Serine protease inhibitor Kazal type 5 (SPINK5) is implicated as a tumor suppressor in head and neck cancers, yet its role in laryngeal cancer progression and metabolic reprogramming remains unclear." (PMID 42062847, 2026).
hepatocellular carcinoma (1 paper, 2021). A malignant tumor that arises from hepatocytes. "BIRC5, SPINK5, SPP1, CACYBP, RAET1E, and NR0B1 were significantly up-regulated, and S100A8 was significantly down-regulated in hepatocellular carcinoma samples based on TCGA-HCC dataset." (PMID 33568167, 2021).
laryngeal carcinoma (1 paper, 2026). Carcinoma that arises from the laryngeal epithelium. "Our results highlight SPINK5 as a tumor suppressor gene for laryngeal cancer progression, providing new insights into its molecular pathogenesis." (PMID 42062847, 2026). "SPINK5 acted as a tumor suppressor, inhibiting laryngeal cancer cell growth and migration." (PMID 42062847, 2026). "SPINK5 knockdown enhanced the activity of KLK6 and the activation of the PI3K/AKT/mTOR signaling pathway in laryngeal cancer cells." (PMID 42062847, 2026). "Besides, western blotting, CCK-8, colony formation, and migration assay were used to investigate the expression of SPINK5, Glucose Transporter 1 (GLUT1), and Hexokinase II (HK-II), and growth and migration capacities of laryngeal cancer cells." (PMID 42062847, 2026).
neutropenia (1 paper, 2025). A decrease in the number of neutrophils found in the blood. "SPINK5, RELA and CARD11 were retrieved and seem to be consistent with the clinical picture characterized by neutropenia associated to immune dysregulation." (PMID 40725177, 2025).
otitis media (1 paper, 2022). Inflammation of the anatomical structures of the middle ear, which is most often caused by an infectious process. "A shift in the Microbacteriaceae family abundance has been recently linked to the susceptibility to the otitis media in outer ear skin due to SPINK5 gene variants." (PMID 35849580, 2022).
prostate adenocarcinoma (1 paper, 2022). "Here, we confirm these findings that Spink1 and Spink5, serine protease inhibitors of Kazal-type, are downregulated by miR-32 both in normal prostate and prostate adenocarcinoma." (PMID 35228520, 2022).
squamous cell carcinoma (1 paper, 2022). A carcinoma arising from squamous epithelial cells. "The inhibitory effect of SPINK5 on KLK5 and the activation of the Hippo pathway may be important factors controlling the molecular landscape of the occurrence and development of squamous cell carcinoma." (PMID 35223512, 2022). "In fact, the lack of SPINK5 is indeed closely related to tumor progression, especially that of squamous cell carcinoma." (PMID 35223512, 2022).
T-cell immunodeficiency (1 paper, 2024). A broad classification of disorders that affect the cell-mediated aspect of the immune response. "We exclude the presence of primary T cell immunodeficiency in Spink5 cKO mice, because the expression level of Aire was unchanged, there were no abnormalities in the number of T regulatory cells in the thymus, spleen or lymph nodes, and there were no changes in the TCRα repertoire." (PMID 38316920, 2024).
thymic atrophy (1 paper, 2024). "Systemic inflammation in Spink5 cKO mice correlates with disease severity and is associated with thymic atrophy and enlargement of lymph nodes and spleen." (PMID 38316920, 2024). "Our findings do not support a role of systemic bacterial infection as a cause for thymic atrophy in Spink5 cKO mice." (PMID 38316920, 2024). "Thymic atrophy and the increased blood neutrophil counts in Spink5 cKO mice correlate significantly with skin lesion severity and are independent of bacterial infection." (PMID 38316920, 2024). "Moreover, systemic treatment of Spink5 cKO mice with broad-spectrum antibiotics cocktail, despite eliminating bacteria in internal organs and skin, did not reduce skin lesion severity, thymic atrophy and blood neutrophil counts." (PMID 38316920, 2024).
viral infections (1 paper, 2017). "As destruction of infected cells is key for antigen presentation in the immune response to active viral infections, increased SPINK5 expression may be a protective measure." (PMID 28552993, 2017).
tumor (24 papers, 2013 to 2026). "Alternatively, deletion and silencing of several genes of interest, Mapk14, Hopx, and Spink5, have been associated with several tumor types, as well." (PMID 25474466, 2014). "Later studies revealed SPINK5 may be associated with tumor biological behavior." (PMID 37185487, 2023). "A deeper analysis revealed upregulation of genes involved in tumor suppression (Clca2, Spink5, Igfbp6, Nptx1, Bex4, Gadd45g, Yipf5), immune regulation (IL6ra, Ccl6, Cd81, Cd244a, Cd151, and Gata4), apoptosis, and pyroptosis (Ddit3, Rgs6, and Gsdmsc2/3/4)." (PMID 39946195, 2025). "HPV-16 E6 was shown to induce cell growth in ESCC by activating the Wnt/β-catenin pathway and SPINK5 acted as a tumor inhibitor in ESCC through blocking the Wnt/β-catenin pathway." (PMID 35241028, 2022). "Others also have recognized SPINK5 as a novel tumor suppressor that suppresses migration and invasion of HNSCC cells." (PMID 34231338, 2021). "Moreover, EHMT2 silencing suppressed tumor growth and inhibited Wnt/β-catenin signalling, effects that were negated when SPINK5 was knocked down." (PMID 40872585, 2025). "miR-32 inhibits SPINK5 expression in castration-resistant PC, promoting tumor development." (PMID 40872585, 2025). "Targeting SPINK5-mediated immune suppression to restore anti-tumor immunity could improve the effectiveness of immune checkpoint therapies, including anti-PD-1/PD-L1 and anti-CTLA-4 treatments." (PMID 40872585, 2025). "SPINK5 plays a tumor inhibitor role in NSCLC by negatively regulating PSIP1." (PMID 38750571, 2024). "The results showed that the knockdown both of SPINK5 and G9a could enhance the proliferative, migratory, and invasive abilities of tumor cells compared with those observed in G9a knockdown only." (PMID 34336110, 2021). "A starting point may be the HTICS Cell migration pathway genes (Nrp1, Npy, Cldn8) and their substitutes (Klrd1, Spink5, Itga8) identified herein—but other known markers of cancer cell dissemination or circulating tumor cells may be equally informative." (PMID 28632792, 2017). "The remaining three genes (e.g., CADM1, SPINK5 and TUSC3) were identified as tumor suppressor genes." (PMID 36675007, 2023). "Among low-frequency MSI events, SMAP1, CCDC168 and SPINK5 harbour frameshift mutations in COAD and UCEC but not in STAD tumours." (PMID 28585546, 2017).
cancer (9 papers, 2017 to 2025). A tumor composed of atypical neoplastic, often pleomorphic cells that invade other tissues. "Examination of the second gene list (current vs. never smokers) revealed that all genes of our signature of smoking, except SPINK5, were upregulated in current smokers without cancer." (PMID 31506599, 2019).
genetic disease (5 papers, 2017 to 2025). "This latter condition is a rare genetic disease caused by mutations in SPINK5, encoding the key serine protease inhibitor LEKTI in the epidermis leading to AD-like skin symptoms." (PMID 32903402, 2020).
bacterial infection (2 papers, 2024 to 2025). "Thus, the thymic atrophy in Spink5 cKO mice is independent of skin or systemic bacterial infection and is most probably induced by stress and the resulting inflammatory milieu." (PMID 38316920, 2024).
respiratory disease (1 paper, 2024). "We also analyzed SPINK5 by WB and observed reduced expression of a proteolytically cleaved species in individuals with WFDC2 mutations compared with healthy control and respiratory disease control groups." (PMID 38626355, 2024).
SPINK5 also shares sentences with these, for which no sentence is quoted: congenital ichthyosis (5 papers); inflammatory skin disease (5); skin disorder (5); Allergy (4); allergic rhinitis (3); autosomal recessive congenital ichthyosis (3); ichthyosiform erythroderma (3); alopecia (2); dermatitis (2); Failure to thrive (2); prostate carcinoma (2); Pruritus (2); Alopecia universalis (1); autoimmune disease (1); Carvajal syndrome (1); chronic granulomatous disease (1); colitis (1); colorectal cancer (1); eating disorder (1); ectodermal dysplasia (1); emphysema (1); endocarditis (1); enteropathy (1); eosinophilia (1); epidermolytic ichthyosis (1); fungal infections (1); Harlequin ichthyosis (1); hyper-IgE syndrome (1); hyperthyroidism (1); hypogammaglobulinemia (1).
A further 26 diseases each share a sentence with SPINK5 in 1 paper.